FOXP3 (forkhead box P3)
Diseases named in the same sentence as FOXP3 in open-access papers (continued):
Sharing a sentence is not in itself a finding about the gene and the disease.
tumor (continued). "Serial analysis of tumor tissue and blood revealed that LCRT led to a consistent decrease in both cytotoxic (CD8+) and regulatory (FOXP3+) T cells during treatment, with partial recovery by 12 weeks." (PMID 40741211, 2025). "This suggests that Foxp3, IL-10, and TGF-β1 collaboratively create an immune suppressive microenvironment by attracting immune suppressive cells and hindering anti-tumor immune cell infiltration." (PMID 41438510, 2025). "In the tumor tissues of Hepa1-6 cells with Acvr2a KO and Ldha KD, the number of infiltrating CD8+ T cells was increased, while the number of Foxp-3+ Treg cells was decreased." (PMID 40139191, 2025). "Therapeutic blockade of this axis using monoclonal antibodies restores anti-tumor immunity by augmenting CD8+ T cell proliferation and cytokine production while reducing Treg-mediated immunosuppression (FoxP3+ cell depletion >40 %)." (PMID 41209702, 2025). "The accumulation of CD4/FOXP3 Treg cells and CD206 M2 macrophages in the tumor, as stained by IF, was significantly lower in the UMSC/miR-124-PD-1 treated group compared to other treatments." (PMID 40134003, 2025). "Tumor size, Ki-67, Caspase-3, intratumoral infiltrated CD4+, CD8+ and FOXP3+ cells were detected immunohistochemically." (PMID 40843004, 2025). "Our analysis revealed distinct expression patterns of CASP1, FOXP3, and PDIA3 between normal and tumor tissues, highlighting their potential roles in shaping the tumor immune microenvironment." (PMID 41150760, 2025). "Low glucose also induces the expression of the transcription factor forkhead box P3 (FoxP3), which converts anti-tumor CD4+ effector T cells (Teff) cells into pro-tumor regulatory T cells (Treg)." (PMID 39796781, 2025). "Cells isolated from the spleens and tumor tissues were stained for surface markers (CD45, CD3, CD4, and CD8) and intracellular markers (granzyme B, IFN-γ, TNF-α, and FoxP3)." (PMID 40969744, 2025). "T cell accumulation was significantly higher in the spleen and within the tumor microenvironment, with elevation in activation markers such as Interleukin-17, CD69, NKG2D, and FasL and a decrease in Interleukin-10 and FoxP3 expression." (PMID 41096863, 2025). "FOXP3+ regulatory T cells (Tregs) and CD45 + RO memory T cells were also identified within the tumour." (PMID 40316725, 2025). "To further explore survival relationships between tumor NOS2 and COX2 expression relative to T cells, PD1, PDL1, and FOXP3 immunosuppressive markers, we evaluated the ratios of the percentage of cells expressing each marker to tumor NOS2 or COX2." (PMID 40663402, 2025). "They observed a significantly higher distribution of CD8+ and CD4+ Tumour-Infiltrating Lymphocytes (TILs), which exhibit a small fraction of infiltrating CD4+ Foxp3+ Tregs indicating clinical effectiveness." (PMID 40852716, 2025). "Downregulation of tumor suppressors, such as FOXO3 and IRF1, and increased FOXP3 and pAKT1, were observed." (PMID 40924302, 2025). "These inhibitors improve the CD8+ cytotoxic T cell to regulatory T cell (CD4+FOXP3+) ratio, modulate cytokine levels (including IL-4, IFN-γ, and TNF-α), and enhance the tumor immune microenvironment." (PMID 40573881, 2025). "225Ac-anti-CCR8 RIT-treated tumors were analyzed immunohistochemically for FoxP3 and CCR8 expression while mechanistic studies of tumor-infiltrating lymphocytes were done by flow cytometry." (PMID 41035646, 2025). "The pathway produces 3-hydroxy-octylamino benzoic acid, a metabolite increasing Foxp3 + Treg cell appearance in an NCOA7-dependent manner, contributing to an immunosuppressive tumor microenvironment." (PMID 40696413, 2025). "Gal1‐induced TAMs recruited CD4+CD25+Foxp3+CCR6+ Tregs through the CCL20‐CCR6 axis and culminated in impaired anti‐tumor immune responses in HCC." (PMID 39853961, 2025).
tumor (continued). "To verify this hypothesis, we subsequently conducted IHC and WB analyses on the tumor tissue and found that both B68 and B1 significantly reduced the expression of PD‐L1 in the tumor tissue, as well as the expression of immune‐suppressive factors such as Foxp3." (PMID 39721027, 2025). "Treatment with CB + miR + R/PGA-SLN-CSW increased cytotoxic (CD8+) and helper (CD4+) T cell populations, reduced FoxP3+ regulatory T cells, and depleted CD206+ M2-type TAMs within the tumor and/or spleen." (PMID 41304839, 2025). "We also examined the relationship between GALNT7 staining and tumor cell PD-L1 positivity, Tn antigen H-score, and infiltration of CD8+ TILs, CD4+ TILs, Foxp3+ TILs, and CD163+ macrophages, stratified by MMR/MSI status." (PMID 40824763, 2025). "The microenvironment of tumor seeded with V583 demonstrated increased density of CD4+ (49.85 vs 16.46 cells/mm2, p = 0.02 unpaired t-test) and CD4 + FoxP3+ (4.85 vs 1.81 cells/mm2, p = 0.04) cells in the tumor microenvironment." (PMID 41322090, 2025). "The numbers and percentages of tumor-infiltrated suppressor cells such as MDSCs (CD11b+Gr-1+) and Tregs (CD45+CD4+FoxP3+) also remained at a similar level." (PMID 40134427, 2025). "Histopathological and immunohistochemical analyses assessed changes in tumour tissue, cell proliferation (Ki-67), angiogenesis (CD31), immune cell infiltration (CD8+ T cells), regulatory T cells (FoxP3+), and programmed death ligand 1 (PD-L1) expression." (PMID 40247360, 2025). "In BC, HAT1 from the GNAT family induces histone H3 acetylation at the CCR4 promoter in Tregs through the FOXP3/HAT1 complex, promoting Tregs infiltration in the tumor microenvironment and tumor cell immune evasion." (PMID 40313963, 2025). "Another study depicted the prognostic impact of studying CD8(+), FOXP3(+), and CD163(+) cell density separately in the tumor center and the invasive front, stressing the significance of considering immune cell distribution." (PMID 40243442, 2025). "Flow cytometry analysis further confirmed that CCR8+ Tregs highly express FOXP3 and CD25, along with immunosuppressive molecules such as CTLA4 and CD39, supporting their role as strongly suppressive tumor-localized Tregs." (PMID 41323783, 2025). "The results indicated that the number of intratumoral FOXP3+ Treg cells was significantly (p < 0.05) decreased following treatment with GSE and AA by 26.29% and 21.86%, respectively, compared to tumor sections from SEC-bearing mice." (PMID 40843004, 2025). "High tumor‐infiltrating lymphocyte (TIL) density correlates with better prognosis, whereas increased FOXP3+ regulatory T cells (Tregs) and M2‐polarized macrophages predict worse outcomes." (PMID 41407509, 2025). "Univariate analysis revealed that diagnosis, preoperative treatment, tumor location, CD3+, CD8+, and Foxp3+ cell infiltration, as well as CTLA-4 and PD-1 expression, significantly impacted PFS." (PMID 39958339, 2025). "Interestingly, the subcellular localization of FoxP3 in Tregs may be vital in tumor progression." (PMID 41511327, 2025). "In patients with available tumor expression data (n = 70) from the MMA cohort, PD-1, PD-L1, FOXP3 and miR-155 gene expression levels were assessed in relation to demographic and clinicopathological features." (PMID 40806346, 2025). "Among others the NSND‐OSCC has higher numbers of TILs, including CD4‐positive, CD8‐positive, and FoxP3‐positive‐cells, which indicates that the NSND‐OSCC is a highly immunological active tumor." (PMID 39462876, 2025). "The combination of all three inhibitors resulted in a tumor microenvironment characterized by increased IFNγ-producing CD4+ T cells, decreased CD4+FOXP3+ T regulatory cells (Tregs), and decreased IL-10-producing CD4+ T cells." (PMID 40904502, 2025). "In the specialized regions of liver metastases, immune cells often exhibit high expression of Foxp3, VEGFR‐2, and PD‐L1, along with diminished antigen‐presenting capabilities and compromised tumor‐killing functions." (PMID 40027151, 2025).
tumor (continued). "The results confirmed that, compared to the pLCR group, the tumor and lymph node tissues of the nLCR group had significantly higher infiltration of regulatory T cells (CD3+ CD4+ FOXP3+)." (PMID 40759637, 2025). "The association between elevated T-reg cell percentages (CD4 + FOXP3 +) at the tumor core and worse CSS in patients in our study might also indicate the existence of an intratumoral immunosuppressive environment that allows tumor cells to evade immune surveillance." (PMID 39751643, 2025). "Spatially, these T cells appeared in much closer proximity to tumor cells, CD163+ macrophages and FOXP3+ Tregs." (PMID 40948758, 2025). "Specific cytokines, such as FOXP3, TNF-α, and IFN-γ, regulate tumor immunity, often with elevated expression in CRC." (PMID 40297577, 2025). "CD4+CD25+Foxp3+ Tregs are induced by COX-2/PGE-2 secretion from ovarian cancer cells, promoting tumor growth." (PMID 40136652, 2025). "This study demonstrates the clinical feasibility of ASO therapy, with generally manageable adverse events, FOXP3 knockdown, and ASO delivery to the tumor." (PMID 39937271, 2025). "ITGA5+ PanCK+ tumor cells, corresponding to the Carcinoma 3 cluster, were localized at the tumor–stroma boundary, and CXCR6+ FOXP3+ CD3D+ regulatory T cells were observed in close proximity within the adjacent stroma." (PMID 40776410, 2025). "GSE and AA enhanced tumor immune microenvironment through increasing CD8+ and CD4+ T cells accompanied by decreasing FOXP3+ Treg cells infiltrated in tumors." (PMID 40843004, 2025). "Instead, it recruited a large number of CD4T_FOXP3+ regulatory T cells by highly expressing CCL5 and binding to the tumor chemokine CCR4 axis, forming a dense immunosuppressive “chemical barrier”." (PMID 40948762, 2025). "CD4+Foxp3+ Treg cell frequencies were substantially reduced in all peripheral lymphoid organs analyzed as well as in the tumor, whereas CD4+Foxp3- conventional T cell frequencies were only slightly reduced in draining (dLN) and control lymph nodes (cLN)." (PMID 40977681, 2025). "The infiltration of lymphocytes into the tumor tissue was assessed using the markers CD3, CD8, and FoxP3." (PMID 40497965, 2025). "The concentration of intratumoral lactate and the proportion of Treg cells were markedly elevated in the tumor tissues, while CD8+ T cell infiltration was mild, resulting in the downregulation of the CD8/Foxp-3 ratio." (PMID 40139191, 2025). "Immune cell infiltration levels, including CD4, CD8, FOXP3, CD163‐positive cells and expression levels of TGFβ1 and SMAD3 proteins in tumor tissue were evaluated by immunohistochemistry." (PMID 41187938, 2025). "Tumor biopsies from 95 EU and 56 LATAM GCs were profiled with immunohistochemistry (CD3, CD8, FOXP3, PD-L1, MSI and HER2), Nanostring mRNA expression analyses, and microbiome sequencing." (PMID 40113862, 2025). "In conclusion, our results highlight the prognostic relevance of FOXP3 expression in advanced-stage tumors and point to a complex interplay between FOXP3, PD-L1, and miR-155 in the OSCC anti-tumor immune response." (PMID 40806346, 2025). "Tregs are immune-suppressive T cells characterized by high expression of FOXP3, CD25, and CD4, which play an important role in suppressing anti-tumor immunity." (PMID 40696413, 2025). "A significant association between PD-L1 expression subgroup and the number of tumour-infiltrating CD4+ T cells, Foxp3+CD4+ T cells, and M2 macrophages was found." (PMID 38541208, 2024). "This hypothesis may be supported by our finding that high CD25+, FOXP3+, and CD25+FOXP3+CD45RA− stromal cell counts were all significantly associated with both high CD8+ TIC count and MSI-high, as MSI is known to cause high tumor mutation burden (TMB), leading to activation of antitumor immunity." (PMID 39232704, 2024). "Thirdly, the correlation of FoxP3 expression with the metastasis, relapse, and overall survival of HCC patients should be investigated to further confirm the tumor suppressor role of FoxP3 in HCC." (PMID 39073490, 2024).
tumor (continued). "This pattern was also observed for the TPK1 tumour cells and both CD4 + FOXP3 and CD8 + CXCL13 + ITGAE immune cells in the high-score group." (PMID 38730464, 2024). "Regulatory T cells (Tregs) are a subset of CD4+ T cells that influence tumor immunotherapy and vaccine activation by CD4, CD25, and FOXP3 expression." (PMID 38751938, 2024). "Their tumor tissues also had higher IDO1 and FoxP3 expression than tumor tissues from PS-conditioned medium-treated or non-treated mice." (PMID 38540186, 2024). "IL-1β is also involved in maintaining immunomodulatory Foxp3+ROR-γt+ (Treg17) cells, which contribute to mucosal homeostasis, tumor immune evasion and autoimmunity control." (PMID 39050547, 2024). "Small molecule AKT activator, SC79, impaired the growth of poor immunotherapy responder murine tumours, B16 and EMT-6 suppressing CD4+Foxp3+Treg TILs through the conversion of Tregs to IFNγ+CD4+Th1-like T cells." (PMID 38704478, 2024). "Further studies have revealed that TILs, such as CD8+ T cells and CD4+ T cells, including Foxp3+CD4+ T cells subset, are known to induce PD-L1 expression on tumour and immune cells in a number of types of cancers, including NSCLC." (PMID 38541208, 2024). "In murine studies, we observed a significant inhibition of tumor growth, while 13.6% (MC38) to 22% (TC1) of tumors were completely resorbed, in conjunction with ~50% decrease of Foxp3 mRNA by qPCR and decreased numbers of intratumoral Tregs." (PMID 39234236, 2024). "Further, in the entire cohort, the expression of COMP in the stroma was correlated with exclusion of different populations of immune cells (CD8+, CD3+, FoxP3+, CD20+) from the tumor microenvironment." (PMID 38563861, 2024). "Lactate promotes CTLA-4 expression in a Foxp3-dependent manner and promotes ubiquitin-specific peptidase 39 (USP39)-mediated RNA splicing in tumor-infiltrating Treg cells." (PMID 39464313, 2024). "Since most FoxP3+ cells also express CD4, this indicates that the proportion of regulatory T cells versus helper T cells increased during tumor progression." (PMID 38812785, 2024). "We further went on to identify that Zn supplementation during tumor development alters mainly CD4 T-cell subtypes by suppressing the T helper 1 (Th1) cell population and enhancing the Foxp3+ Treg cell population." (PMID 39247196, 2024). "To confirm the differences found in mRNA markers for T‐cell infiltration in tumors between Panx1 genotypes, we performed IF staining on PLP‐fixed tumor cryosections to verify the presence of CD4+, CD8+, and Foxp3+ lymphocytic cells." (PMID 38327091, 2024). "To analyze the characteristics of the TIME in different tumor regions, we first detected the expression of immune markers including CD4+, CD8+, Foxp3+, CD20+, CD68+, LAMP3+, PD-1+ TILs, and PD-L1 in different tumor regions using IHC." (PMID 38254190, 2024). "Significant correlations between PD-L1+ lymphocytes and tumour-infiltrating CD4+, Foxp3+CD4+, IL-17A+CD4+ T cells and M2 macrophages were found." (PMID 39409156, 2024). "Although P3CA-AR-V7 tumors displayed an immunosuppressive phenotype enriched with FoxP3+ Tregs which allowed their growth in immunocompetent mice, we hypothesized that the antigen-specific responses produced by Ad-AR-V7 may be capable of eliciting anti-tumor responses in a preventative setting." (PMID 39591176, 2024). "Tumor hypoxia was assessed using pimonidazole and CA IX immunohistochemistry, and T cell infiltration by CD3 and FoxP3 staining." (PMID 39650654, 2024). "The markers used to characterize the immune and tumor compartments of the iTME were: CD3, CD4, CD8a, FOXP3, PD-1, PD-L1, CD68, CD33, and pan-keratin (PanCK)." (PMID 38898200, 2024). "We collected tumor tissues from B6 albino males 7 days post-implantation, and stained for CD8, FoxP3, and CD4." (PMID 39591176, 2024). "The first panel featured staining for tumor cells (pan-CK+), B cells (CD20+), CD4+ and CD8+ T cells, Tregs (CD4+FOXP3+), and macrophages (CD68+)." (PMID 38994676, 2024).
tumor (continued). "In the TME of the TC-1 tumor, the T cell compartment, consisting of CD8+ and CD4+ Tconvs and FOXP3+ Tregs, comprised only 11.1% of the CD45+ hematopoietic cell infiltrate, as identified by flow cytometry." (PMID 38349740, 2024). "Then, we evaluated the correlation between expression of LGALS3 in tumor and gene expression levels of FOXP3, CD4, and CD8 in tumor and stroma area samples that were microdissected from FFPE samples." (PMID 37567864, 2024). "Additionally, CD4+ T cells that express the forkhead box P3 (FoxP3) transcription factor function as regulatory T (Treg) cells and either directly or indirectly induce immunosuppression, both promoting immune tolerance and actively inhibiting anti-tumor immune responses." (PMID 38672372, 2024). "Biopsy histology confirmed the presence of a larger number of tumor-infiltrating CD4+ and CD8+ T-cells and persistent low numbers of Foxp3+ cells following repeated G47∆ treatments." (PMID 38921005, 2024). "It was found that FoxP3 was lower expressed in HCC tissue compared to that in para-tumor tissue, in contrast, CD133 level was higher in tumor tissue (HLivH180Su10, Xinchao Biotech, Shanghai, China)." (PMID 39073490, 2024). "In our results, FOXP3 was negatively correlated with serine, therefore it is possible that serine can affect the TME, resulting in tumour proliferation and progression." (PMID 38332687, 2024). "To investigate this, we compared glycolytic parameters among tumor cells and CD8+ T cells, CD4+Foxp3– cells (effector T cells [Teffs]), and CD4+Foxp3+ cells (Tregs) within the TME from established B16-YFP tumors excised from mice treated with LDHi for 10 days." (PMID 39225102, 2024). "PI3Kδ plays an important role in the maturation of Foxp3+ Treg cells, and inhibiting PI3Kδ can effectively improve the immune suppressive microenvironment in CRC tumor-bearing mice." (PMID 39262952, 2024). "To examine the influence of FOXP3 in tumor architecture, we implanted PARCB2 FOXP3Δ3 and PARCB2 FOXP3 lines into immunocompromised NOD-scid IL2Rgammanull (NSG) mice." (PMID 39099201, 2024). "Currently, the IHC-based identification of many TIL-specific markers is one of the main methods for identifying the lymphocyte infiltrates in the TME (including FOXP3, CD3, and CD8) on successive tumor tissue slices." (PMID 39712007, 2024). "As immune-mediated tumor rejection becomes more pronounced (higher ICR immune subtype), it appears that effector T cells are found at greater distances from CD3+FoxP3+ T cells, which mainly perform immune regulatory function in this context." (PMID 38375478, 2024). "The observed reduction in the percentage of CD4+ FoxP3 + regulatory T cells, while sparing CD8+ T cells, can lead to de-suppression of anti-tumor immune response and reduce tumor growth." (PMID 38503797, 2024). "Overexpression of FOXP3 increases the infiltration of CCR4+Tregs cells, leading to reduced anti-tumor immune response and tumor progression." (PMID 38919615, 2024). "Immune cells infiltrating into tumor tissue displayed broad inter-individual differences in the density of immunohistochemically stained cells, with CD3+, CD8+ and FOXP3+ cell counts varying significantly among the samples." (PMID 38704243, 2024). "Significant tumor microenvironment changes were observed in pCR patients, including reduced VEGF+ cells and CD4+Foxp3+ Treg cells, and increased perivascular CD4+ T cells, CD39+CD8+ T cells, and M1 macrophages." (PMID 39465257, 2024). "These conditions were extensively studied in preclinical research which provided a description of the complex modulation of the CD8+ anti-tumor response involving the immunosuppressive activity of CD4+ and FOXP3 lymphocytes." (PMID 38638854, 2024). "Most inflammatory biomarkers evaluated at screening were positively correlated with one another (tumor inflammation four-gene signature score, CD8+ TILs, FoxP3+; PD-L1+ to a lesser extent), except for TMB." (PMID 39025948, 2024).